MMP9 (matrix metallopeptidase 9)
Diseases named in the same sentence as MMP9 in open-access papers (continued):
Sharing a sentence is not in itself a finding about the gene and the disease.
glomerulonephritis (11 papers, 2014 to 2025). A renal disorder characterized by damage in the glomeruli. "MMP9 is essential for migrating and recruiting macrophages into the glomerulus in glomerulonephritis." (PMID 38017559, 2023). "Mmp-9 also plays a critical role in recruiting leukocytes to sites of injury after peripheral nerve crush in rats, glomerulonephritis in mice, and cryoinjury in zebrafish." (PMID 35271573, 2022). "MMP-9 protects mice by promoting the decomposition of glomeruli fibrin caps during glomerulonephritis via fibrinolytic activity." (PMID 30186548, 2018). "Sato10 and his colleagues investigated the serial changes of glomerular metalloproteinase activity in antithymocyte-induced glomerulonephritis in rats and found attennated glomerular MMP-9 activity." (PMID 26430407, 2015). "MMP9 is also involved in the recruitment of pro-inflammatory macrophages in experimental glomerulonephritis." (PMID 24454919, 2014). "MMP-9 is particularly important in the progression of human glomerulonephritis." (PMID 40045202, 2025). "MMP-9, a protease that cleaves collagen IV, a major component of the glomerular basement membrane, plays an important role in the abnormal mesangial proliferative changes in human glomerulonephritis, including LNs." (PMID 40045202, 2025). "Exclusion of patients with glomerulonephritis as cause of ESRD did not affect results; n = 46, OPG: p = 0.054 and MMP-9: p = 0.018 (t-test)." (PMID 33326471, 2020).
Kawasaki disease (11 papers, 2014 to 2026). A rare inflammatory disease characterized by an acute febrile, systemic, self-limiting, medium-vessel vasculitis primarily affecting children. "Five biomarkers-CD177, Matrix Metallopeptidase 9, Nuclear Factor Erythroid 2, Colony Stimulating Factor 3 Receptor, and Suppressor Of Cytokine Signaling 3-were consistently upregulated in Kawasaki disease and showed high diagnostic accuracy (area under the curve >0.94 in both datasets)." (PMID 41743406, 2026). "On the other hand, the MMP-9, TIMP concentrations, and the MMP-9:TIMP ratio were diminished in patients with Kawasaki disease (KD)." (PMID 34940542, 2021). "Similarly, the hypomethylation of the MMP9 gene and the aberrant upregulation of MMP9 expression is observed in Kawasaki disease, a pediatric vascular disease characterized by inflammation of the coronary arteries." (PMID 33920915, 2021). "In the future, large sample and long follow-up studies are needed to verify the role of MMP-9, PLTs, ESR, and CRP levels in Kawasaki disease with cardiovascular injury." (PMID 36159562, 2022). "Specifically, cell distribution differences of MMP-9 and the tissue inhibitor of MMP-1 in patients with Kawasaki disease." (PMID 25191698, 2014). "Interestingly, elevated plasma levels of MMP-9, TIMP-1, and VEGF have also been found in the acute phase of Kawasaki disease, but not later, even in the presence of persistent coronary aneurysms." (PMID 34572455, 2021).
keloid (11 papers, 2007 to 2025). An irregularly shaped, elevated mark on the skin caused by deposits of excessive amounts of collagen during wound healing. "Nevertheless, aberrant upregulation of MMP9 was associated with excessive granulation tissue formation, impaired healing, and the potential development of keloids." (PMID 41295412, 2025). "Matrix metallopeptidase 9 (MMP9) has been implicated in the keloid pathophysiology, due to its gelatinase activity." (PMID 29186868, 2017). "Therefore, more future clinical studies are still warranted to better evaluate the association between MMP-2/MMP-9 and keloid formation." (PMID 39654616, 2024). "In addition, MMP-9 may be regulated by multiple transcription factors, and different transcription factors may have different activities at different stages of keloids formation, causing the MMP-9 expression to exhibit opposite effects in this disease." (PMID 39654616, 2024). "Since both MMP-2 and MMP-9 have been found to be involved in the pathogenesis of keloids development, several potential drugs or substances that targeted the two genes are found to be effective on the treatments or preventions of keloids." (PMID 39654616, 2024). "Dysregulation of this balance not only underscores the significance of MMP-2 and MMP-9 but also opens new avenues for exploring targeted therapies for keloids." (PMID 39654616, 2024). "In summary, this review consolidates our current understanding of MMP-2 and MMP-9 in keloid pathogenesis, shedding light on their intricate involvement in the dysregulated keloids processes." (PMID 39654616, 2024). "According to the experimental and clinical data, MMP-9 expression levels are usually elevated in keloid tissue." (PMID 39654616, 2024). "In summary, this review consolidates the current understanding of MMP-2 and MMP-9 in keloid pathogenesis, shedding light on their intricate involvement in the dysregulated keloids processes." (PMID 39654616, 2024). "Conversely, the upregulation of MMP-2 and MMP-9 have also been reported to inhibit keloid formation." (PMID 39654616, 2024). "Up to date, only two eligible studies belonging to clinical researches implied the roles of MMP-2/MMP-9 on keloid formation." (PMID 39654616, 2024). "This comprehensive review extensively illustrates intricate roles of MMP-2 and MMP-9 in the regulation of keloids." (PMID 39654616, 2024). "A previous pilot study demonstrated that the medians levels of both MMP-2 and MMP-9 were increased in the hypertrophic scar and keloid groups as compared to the donor skin." (PMID 39654616, 2024). "As a result, more studies are still warranted to confirm the exact role of MMP-9 in the development and progression of keloid formation." (PMID 39654616, 2024). "Further, the expression level of matrix metalloproteinase (MMP)-9 in keloid tissue explants transduced with dEl-k35/sLRP6E1E2 was significantly increased in comparison to dE1-k35/LacZ-treated keloid tissue explants." (PMID 29118355, 2017). "Though the role of MMP9 in keloid development is incompletely studied, several reports reveal its active role in the development of keloid lesions." (PMID 29186868, 2017). "Transforming growth factor beta 1 (TGF-β1)-mediated up-regulation of microRNA-21 increases the expression of MMP9 in keloid fibroblasts, wherein it promotes fibroblast proliferation and transdifferentiation." (PMID 29186868, 2017). "MMP9 is significantly overexpressed in keloid-derived fibroblasts, especially at the margins of the keloid wound." (PMID 29186868, 2017). "On the other hand, by analyzing the expression patterns of MMP-2, MMP-9 in a patient’s keloid tissue, it may be possible to predict the response to different pharmacological interventions and tailor the treatment accordingly." (PMID 39654616, 2024). "The expression levels of some inflammatory cytokines and growth factors are also often elevated in keloid tissues, and these factors may stimulate fibroblasts to secrete MMP-9, further exacerbating keloid fibrosis." (PMID 39654616, 2024).
keloid (continued). "Nevertheless, the present study revealed that developing more efficient drug delivery systems on MMP-2 and MMP-9 may be one of the successful treatments for managing keloids." (PMID 39654616, 2024). "High level of MMP-9 is found to degrade collagen, elastin, and other components of the extracellular matrix and promotes the migration and proliferation of fibroblasts, which leads to the continuous expansion of keloid tissue." (PMID 39654616, 2024). "The reviewed studies demonstrate elevated expression levels of MMP-2 and MMP-9 in keloid tissue compared to normal skin, suggesting their pivotal role in driving the excessive collagen deposition and altered tissue architecture observed in keloids." (PMID 39654616, 2024). "Since accumulating evidence has shown that gelatinases played a crucial role in the process of keloid formation, we summarized the current knowledge on the association between MMP-2 and MMP-9 expression and the pathological process of keloids through a comprehensive review." (PMID 39654616, 2024). "As previously reported, EGF treatment of all dermal fibroblasts significantly induced an increase in MMP-1 expression, and both normal and keloid dermal fibroblasts showed increased MMP-9 expression, whereas hypertrophic dermal fibroblasts showed a significant decrease in MMP-9 expression." (PMID 33672186, 2021). "Additionally, TGF-β1 increased the expressions and activities of MMP2 and MMP9 in keloid fibroblasts, which was suppressed by miR-21 inhibition." (PMID 27554193, 2016). "Therefore, downregulating MMP-9 expression may significantly inhibit keloid development." (PMID 39654616, 2024). "The researchers found that these drugs can alleviate keloids formation by elaborately regulating MMP-2 and MMP-9 expressions." (PMID 39654616, 2024). "dEl-k35/sLRP6E1E2-transduced keloid tissue explants had markedly reduced ECM components and MMP-2 and MMP-9." (PMID 29118355, 2017). "SM22, which is overexpressed in keloids, promotes ECM accumulation through inhibition of MMP-9 expression." (PMID 17718906, 2007). "Taken together, PL may promote keratinocyte epithelialization and enhancing fibroblast matrix deposition by upregulating MMP-9 expression through p38 and ERK1/2 pathway, leading to keloid formation." (PMID 39654616, 2024). "However, the inhibitors of MMP-2 and MMP-9 for treating keloids are not yet available in human trials." (PMID 39654616, 2024).
keratitis (11 papers, 2016 to 2025). A corneal disease that is characterized by inflammation of the cornea. "In comparison to the vehicle-treated group, genipin treatment significantly decreased the expression levels of MMP9 in both S. aureus (p = 0.013) and P. aeruginosa keratitis (p = 0.022)." (PMID 37108070, 2023). "TNF-α is reportedly elevated in corneas from individuals suffering keratitis, and this cytokine has been shown to stimulate MMP-9 activity in HCE cells." (PMID 31003493, 2019). "We identified several genes and pathways involved in the host response to infectious keratitis, including CXCL9, CXCR3, and MMP9 for viral, and S100A8/A9, MMP9, and the IL17 pathway for bacterial/fungal keratitis." (PMID 38274739, 2023). "We identified several specific genes and pathways involved in the host response to infectious keratitis, including CXCL9, CXCR3, and MMP9 for viral, and S100A8/A9, MMP9, and the IL17 pathway for bacterial/fungal keratitis." (PMID 38274739, 2023).
myocarditis (11 papers, 2013 to 2025). Myocarditis is a condition that is characterized by inflammation of the heart muscle (myocardium). "Metastasis-associated lung adenocarcinoma transcript 1 (MALAT1) is involved in cardiac innate immunity in a myocarditis model, and the expression of MMP9 was decreased in MALAT1-deficient bone marrow-derived macrophages." (PMID 35842645, 2022). "Our study demonstrates for the first time that APN up‐regulates MMP‐9 expression in cardiac fibroblasts and myocytes as well as heart‐infiltrating immune cells thereby contributing to elevated cardiac MMP‐9 expression following local tissue injury associated with CVB3 myocarditis." (PMID 29263115, 2017). "Furthermore, increased activity of cardiac MMP-2 and MMP-9 has been associated with mortality during the acute phase of T. cruzi infection, suggesting an important role in the induction of chagasic acute myocarditis." (PMID 24260222, 2013). "The transcription of many MMPs, especially MMP-3, MMP-8 and MMP-9 are upregulated in the acute phase of CVB3-induced myocarditis." (PMID 34452454, 2021). "Moreover, on day 3 and day 7 post CVB3 infection splenic MMP‐9 expression was diminished in APN‐KO mice correlating with attenuated myocardial immune cell infiltration in subacute CVB3 myocarditis." (PMID 29263115, 2017). "Taken together, reduced MMP‐9 expression in immune cells of APN‐KO mice might influence cardiac ECM remodeling in CVB3 myocarditis by two distinct mechanisms, that is, attenuation of collagen degradation and inhibition of immune cell‐mediated tissue injury." (PMID 29263115, 2017). "(2008) demonstrated a protective effect of MMP‐9 in CVB3‐induced myocarditis." (PMID 29263115, 2017). "Persistently enhanced cardiac MMP‐9 expression/activity in the presence of APN results in increased cleavage of accumulating collagens and augmented ECM turnover in CVB3 myocarditis." (PMID 29263115, 2017). "In vivo, compared to WT mice cardiac MMP‐9 activity and serum levels of carboxy‐terminal telopeptide of type I collagen (ICTP) were attenuated in APN‐KO mice in subacute (day 7 p.i.)CVB3 myocarditis." (PMID 29263115, 2017). "In conclusion, by demonstrating that APN up‐regulates MMP‐9 expression in resident cardiac and infiltrating immune cells the results of our study provide a novel mechanism how APN might inhibit adverse cardiac remodeling associated with MI, myocarditis and overload states." (PMID 29263115, 2017). "Several studies have demonstrated an up‐regulation of cardiac MMP‐9 expression and activity in experimental CVB3 myocarditis." (PMID 29263115, 2017). "We show that APN up‐regulates MMP‐9 expression in cardiac fibroblasts and myocytes as well as infiltrating immune cells thus contributing to increased cardiac MMP‐9 activity in CVB3 myocarditis." (PMID 29263115, 2017). "In this study, we found that knocking down the expression of S100A1 significantly attenuated the effects of reynoutrin on improving cardiac function, cardiomyocytes apoptosis, myocardial inflammation and fibrosis, and down-regulating the expressions of MMP2, MMP9, p-p65, and TGF-β1 in rats with IHF." (PMID 34366855, 2021). "In acute (day 3 p.i., data not shown) and subacute (day 7 p.i.)CVB3 myocarditis splenic MMP‐9 expression in WT mice was significantly up‐regulated compared to baseline levels." (PMID 29263115, 2017).
pulpitis (11 papers, 2018 to 2024). Inflammation of the dental pulp. "The measured MMP-9 levels in asymptomatic teeth were found to be half that of teeth diagnosed with reversible pulpitis." (PMID 37753855, 2023). "The MMP9 levels from blood sample of irreversible pulpitis were highly increased compared with those from blood samples of asymptomatic or reversible pulpitis teeth." (PMID 33046027, 2020). "MMP-9 was collected from some teeth affected with pulpitis and thus identified as a possible diagnostic biomarker; however, low yields of the protein resulted in inconsistent recovery of MMP-9 in a significant number of teeth clearly affected with pulpitis." (PMID 30131827, 2018). "However, since MMP9 is increased in dentinal fluid of both reversible and irreversible pulpitis, these two types of pulpitis cannot be distinguished by detecting MMP9 alone at this time." (PMID 38947881, 2021). "MMP-9, a neutrophil-derived MMP, is proposed as a local biomarker useful for distinguishing reversible and irreversible pulpitis because higher levels of MMP-9/total protein in pulpal fluid were significantly associated with the failure of direct pulp capping." (PMID 39917698, 2024). "The molecular characterization of proteins in irreversible pulpitis includes MMP-12, MMP-9, RANTES, MIP-2, MCP-1, MMP-2, MMP-1, and P-Selectin, which exhibited correlations of ≥0.8 with the duration of pain caused by cold." (PMID 38279358, 2024). "LPS activates inflammatory cytokines, such as IL‐1, IL‐6, IL‐8, matrix metalloproteinase (MMP)‐9, MMP‐2, and TNF‐α28, 29, 30 in the pulpitis progress." (PMID 35334501, 2022). "Patients in whom permanent teeth with extremely deep carious lesions were diagnosed as completely asymptomatic (n = 8) or with signs of reversible pulpitis (n = 10) underwent non-selective caries removal followed by a blood test to assess the level of MMP-9." (PMID 37753855, 2023). "Detection was not possible, due to MMP-9 levels below the detection limit in the case of necrotic pulps, as well as no clinical signs of pulpitis." (PMID 33801317, 2021). "In the present study, MMP-2 and MMP-9 were significantly upregulated in LPS-stimulated hDPCs and further repressed by treatment with S14G-humanin, indicating a potential protective effect of S14G-humanin on the impaired ECM during the progression of pulpitis." (PMID 34605740, 2021). "In addition to investigating the possible regulatory mechanisms of DEGs, we screened key genes as biomarker candidates for the diagnosis of pulpitis, including PTPRC, CD86, CCL2, IL6, TLR8, MMP9, CXCL8 and ICAM1." (PMID 33046027, 2020). "Therefore, the aim of this prospective pilot study was to assess the long-term outcome of partial pulpotomy in permanent teeth after carious pulp exposure without signs or symptoms of irreversible pulpitis, verified clinically, radiographically, and via MMP-9 levels." (PMID 37753855, 2023).
vitamin D deficiency (11 papers, 2011 to 2024). A nutritional condition produced by a deficiency of VITAMIN D in the diet, insufficient production of vitamin D in the skin, inadequate absorption of vitamin D from the diet, or abnormal conversion of vitamin D to its bioactive metabolites. "In angiotensin II-induced AAA mice, vitamin D deficiency was associated with increased MMP-9 activity and elastin degradation." (PMID 38923975, 2024). "In future experiments, analysis of GBO under the condition of vitamin D deficiency and MMP-9 inhibitor should be conducted to confirm the contribution of MMP-9 in aberrant GBO in vitamin D deficiency." (PMID 35207806, 2022). "According to the prevalence of vitamin D deficiency in our country, Iran, we aimed to evaluate the relationship between vitamin D status and the level of MMP-9 in patients undergoing percutaneous coronary intervention." (PMID 33841529, 2020). "Based on the present study high levels of TNF-α and IL-6 as well as vitamin D deficiency in studied participants could disturb the MMP-9/TIMP-1 balance and lipid metabolism, leading to plaque formation/ rupture in predisposed CAD patients." (PMID 38357561, 2023). "The present study suggested that high levels of TNF-α and IL-6 and vitamin D deficiency in our studied patients could disturb the MMP-9/TIMP-1 balance and lipid metabolism, leading to plaque formation/ rupture in predisposed CAD patients." (PMID 38357561, 2023). "For example, vitamin D deficiency may enhance inflammation, chemokine production via NF-ƘB, parenchymal degradation, TNF-α, IL-18, histone acetylation, corticosteroid resistance, and matrix metalloproteinase (MMP)-9 production." (PMID 37006939, 2023).
astroglioma (10 papers, 2011 to 2025). "The immunofluorescence analysis of MMP-9 conducted in this study suggests that it is distributed within and between astrocytic tumor cells, supporting MMP-9 secretion and its proposed role in extracellular matrix remodeling, thus promoting tumor cell spread." (PMID 41573658, 2025). "On the other hand, curcumin has also been seen to reduce the expression of MMP-9 in astroglioma cells via inhibition of the PKC to MAPK pathway." (PMID 29642589, 2018). "Expression of MMP2 and MMP9 was elevated by IFN-γ treatment in a human salivary gland cell line (HSG), but IFN-γ inhibits constitutive MMP-2 expression in human astroglioma cells." (PMID 30622567, 2018). "Another study described that nontoxic doses of ginsenoside CK significantly decrease MMP-9 expression, which plays a major part in tumor invasion and angiogenesis, at both the gene and protein levels in astroglioma cells." (PMID 34073155, 2021). "We found that MMP-9/NGAL activity in tumor tissue and Preop-1d urine correlated with the glioma tumor grade and tumor volume (p < 0.05); a similar correlation was observed between MMP-9/NGAL activity and the status of astrocytic tumors (p < 0.05)." (PMID 26663949, 2015).